FGF2 (fibroblast growth factor 2)
Diseases named in the same sentence as FGF2 in open-access papers (continued):
Sharing a sentence is not in itself a finding about the gene and the disease.
anxiety disorder (4 papers, 2018 to 2026). A category of psychiatric disorders which are characterized by anxious feelings or fear often accompanied by physical symptoms associated with anxiety. "In this study, a novel electrochemical biosensor for the detection of fibroblast growth factor-2 (FGF-2), a biomarker associated with anxiety disorders, was developed for the first time." (PMID 41656439, 2026). "During studies on rats, researchers proved that FGF-2 is a promising biological marker for susceptibility to stress and anxiety disorders." (PMID 33920547, 2021). "The obtained recovery values demonstrated that the developed impedimetric FGF-2 immunosensor is highly suitable for real-sample applications and holds significant potential as a reliable tool for the detection of anxiety disorders." (PMID 41656439, 2026). "Moreover, people with a lower starting point of FGF-2 due to stress exposure could have psychological difficulties in coping with stress and, as a result, be more prone to anxiety disorders." (PMID 33920547, 2021). "Thus, FGF2 might also serve as a potential biomarker for anxiety disorders; however, further research is required to elucidate the potential of FGF2 to identify vulnerable individuals and to establish preventative interventions." (PMID 32640734, 2020).
Bell's palsy (4 papers, 2010 to 2025). Partial or complete paralysis of the facial muscles of one side of a person's face. "FGF-2 may exert paracrine/autocrine trophic actions in the facial nucleus and may be relevant as a therapeutic target to Bell's palsy." (PMID 21062430, 2010). "The FGF-2 signaling may be explored in the search of new therapeutic target for Bell's palsy." (PMID 21062430, 2010). "The resulting increase in FGF-2 in the cytoplasm of reactive astrocytes leads to enhanced secretion of FGF-2, which acts in a paracrine and autocrine manner to provide trophic support to the facial nucleus, thereby preventing Bell’s palsy." (PMID 37237902, 2023).
bone cancer (4 papers, 2016 to 2023). A primary or metastatic malignant neoplasm affecting the bone or articular cartilage. "In our understanding of pain research, this is the first report of showing in vivo evidence for the pain-modulatory action of FGF2 in bone cancer pain." (PMID 34203430, 2021). "Therefore, the analgesic action of APT-F2P in bone cancer pain cannot be accounted for by the suppression of tumor proliferation and osteolysis but by some other mechanism involving a novel FGF2 function in pain." (PMID 27506449, 2016). "Hence, the pathophysiological role of FGF2 in bone cancer pain is largely independent from that of NGF." (PMID 27506449, 2016). "We assume that not only NGF but also FGF2 might be overexpressed by bone cancer." (PMID 27506449, 2016). "Since FGF2 is known to stimulate angiogenesis and endogenous VEGF expression, excess FGF2 and VEGF can synergize to induce angiogenesis and increase bone cancer progression." (PMID 34203430, 2021). "Taking these results into consideration, we assume that APT-F2P might be effective in ameliorating chronic pain associated with FGF2 overproduction, such as in bone cancer, but not acute pain unassociated with FGF2 overproduction, such as in immediate postoperation." (PMID 27506449, 2016). "Since FGF2 is known to stimulate angiogenesis and endogenous VEGF expression, excess FGF2 and VEGF can synergize to induce angiogenesis and increase severity of bone cancer progression." (PMID 27506449, 2016).
cardiomyopathy (4 papers, 2018 to 2025). A disease of the heart muscle or myocardium proper. "This study aimed to assess the plasma levels of TGF-β1, active-TGF-β1, VEGF-A, and FGF2 in patients with FD and their correlation with the other progression of FD-associated cardiomyopathy." (PMID 37626912, 2023). "Furthermore, FGF2 was found to mitigate the inflammatory response in LPS-induced septic cardiomyopathy model." (PMID 41292702, 2025). "Microvascular network growth and the angiogenic properties of the TAT in elderly patients with cardiomyopathy also seem to involve the upregulation of PDGFC, FGF2, NOTCH2, FOS, JAG1, and PDGFRA target genes." (PMID 37833902, 2023).
disc degeneration (4 papers, 2008 to 2020). "It was assumed that disc degeneration stimulated or triggered the release of FGF-2 and TGF-β1 by the disc itself." (PMID 27405858, 2016). "The real role of FGF-2 in hAF harvest from degenerated disc tissue still needs to be analyzed to clarify its possible roles in disc degeneration." (PMID 27405858, 2016). "As a consequence, FGF-2 might participate in the process of disc degeneration or repair in the degenerated stage." (PMID 27405858, 2016). "FGF-2 may create a cascade in hAF tissues, where they act and participate in cellular remodeling from the normal stage to disc degeneration and further herniation." (PMID 27405858, 2016). "Clinically, noggin may be a potential target for disc degeneration as it is a well-known inhibitor of the anabolic TGFβ/bone morphogenetic protein signaling pathway and is upregulated by FGF2 in bovine disc tissue." (PMID 18435858, 2008).
Fabry disease (4 papers, 2012 to 2023). Fabry disease (FD) is a progressive, inherited, multisystemic lysosomal storage disease characterized by specific neurological, cutaneous, renal, cardiovascular, cochleo-vestibular and cerebrovascular manifestations. "The combination of increased expression ofTGF-β1 and VEGF caused by Gb3 accumulation may allow upregulation of FGF-2, VEGFR2and P-p38 expression, and these changes may be associated with Fabry disease nephropathyby inducing apoptosis." (PMID 23007467, 2012). "The results showed a clear elevation of FGF2 and IL-7 in Fabry disease compared to all other LDs." (PMID 32370284, 2020). "FGF2, VEGF-A, VEGF-C, and IL-7 have recently been described as a proteomic signature of Fabry disease." (PMID 35268324, 2022). "Another marker of angiogenesis, FGF2, did not correlate with HCM in Fabry disease." (PMID 37626912, 2023).
inflammatory bowel disease (4 papers, 2014 to 2022). A spectrum of small and large bowel inflammatory diseases of unknown etiology. "Subsequently, upregulation of FGF-1 was described in allografts undergoing chronic rejection and in renal inflammation, while elevated levels of circulating FGF-2 were reported in patients with inflammatory bowel disease and eosinophilic esophagitis." (PMID 25638171, 2015).
kidney damage (4 papers, 2014 to 2025). "In this study, we explored the role of FGF-2 and VEGF-A, because both heparin-binding growth factors are accumulated in the kidney of children with HIV-renal diseases, and affect the outcome of HIV-nephropathy in HIV-Tg mice and rats." (PMID 27097314, 2016). "Furthermore, previous studies showed that HIV-Tat and FGF-2, acting in a synergistic manner, increased the activity of Rho-A in podocytes cultured from the urine of children with HIVAN, and precipitated the development of HIV-nephropathy in HIV-Tg26 mice." (PMID 27097314, 2016). "In addition, a reduction in the FGF-2 present in the tissue was observed in the WTG rats, constituting an important result of treatment with 2% L-glutamine as it may indicate a pathological process in the glomerulus suggestive of kidney damage, which is a common finding in chronic kidney diseases." (PMID 37851784, 2023).
lymph node metastasis (4 papers, 2012 to 2026). "Crosstab showing the correlation between miR-155 and FGF2 in patients with lymph node metastasis (N+)." (PMID 22295063, 2012). "We also confirmed that using anti‐FGF2 monoclonal antibody (3F12E7) could inhibit lymphangiogenesis and lymph node metastasis in the orthotopic lymph node metastasis model." (PMID 39119899, 2024). "Taken together, these findings indicate that LNMAC plays a crucial role in FGF2‐mediated lymphangiogenesis and lymphatic metastasis, highlighting that LNMAC might be a therapeutic target for lymph node metastasis in CSCC patients." (PMID 39119899, 2024).
malignant pleural mesothelioma (4 papers, 2015 to 2024). A malignant neoplasm that arises from mesothelial cells in the pleura and shows a diffuse growth pattern. "Moreover, it has been reported that tumor-associated fibroblasts can boost the progression of malignant pleura mesothelioma through a cytokine network involving fibroblast growth factor-2 (FGF-2), platelet-derived growth factor-AA (PDGF-AA), and hepatocyte growth factor (HGF)." (PMID 38462627, 2024). "Importantly, FP‐1039 (GSK3052230), a FGF2 trap molecule, was tested in a clinical phase IB trial for patients with malignant pleural mesothelioma (ClinicalTrials.gov NCT01868022), highlighting that the road leading to development of FGF2 blocking molecules is still rugged but promising." (PMID 39119899, 2024).
metastatic tumors (4 papers, 2006 to 2020). "MBC patients’ exosomes had a low concentration of MIP-3 alpha, IL-23, M-CSF, Eotaxin-3, BLC, SDF-1 alpha, IL-2R, MDC, FGF-2, IL-22, and IL-31, suggesting that metastatic disease may be associated with immune suppression related to low exosomal cytokines." (PMID 32826923, 2020).
myelofibrosis (4 papers, 2022 to 2025). A partial or complete replacement of the bone marrow stroma by fibrous tissue. "Three genes implicated in myelofibrosis were found to be overexpressed in HLC: FGF2 (fibroblast growth factor-2; 500-fold), its receptor FGFR1 (50-fold), and TGFB1 (tumor growth factor ß1; 16-fold)." (PMID 35476232, 2022).
oral cancer (4 papers, 2013 to 2025). "In addition, FGF2 expression was identified to be significantly associated with the presentation of oral cancer." (PMID 24959249, 2014). "Increased mRNA levels of FGF-2 and its receptors were observed in oral cancer and precancer patients as compared to normal controls in the present study." (PMID 26465941, 2015). "Through PPI network construction and module analysis, an FGF2 module was formed and was identified to be significant in the progression of oral cancer." (PMID 24959249, 2014). "In addition, FGF2 formed a module in the PPI network that was constructed based on oral cancer samples, which indicated that FGF2 has an important function in the progression of oral cancer." (PMID 24959249, 2014).
peripheral nerve injuries (4 papers, 2012 to 2025). "As seen with other peripheral nerve injuries, FGF-2 was upregulated in the subscapularis following a preganglionic injury, despite the fibrosis present." (PMID 40501994, 2025). "FGF-2, in contrast, is expressed by Schwann cells both before and after peripheral nerve injury." (PMID 32848626, 2020).
Pleural effusion (4 papers, 2012 to 2023). The presence of an excessive amount of fluid in the pleural cavity. "High FGF2 levels in serum and pleural effusions were previously shown to correlate with poor patient survival in MPM, whereas for other FGFs data are largely missing." (PMID 31527449, 2019). "Moreover, high FGF2 levels in the blood and in pleural effusions have been correlated with tumor aggressiveness and worse prognosis." (PMID 37340889, 2023). "Among the growth factors of the FGF family, high FGF2 was found to have negative prognostic impact in PM both in blood and pleural effusions." (PMID 37340889, 2023).
pneumonia (4 papers, 2015 to 2023). An acute, acute and chronic, or chronic inflammation focally or diffusely affecting the lung parenchyma, caused by an infection in one or both of the lungs (by bacteria, viruses, fungi, or mycoplasma.). "Inhibits neuraminidase activity and influenza virus proliferation in vivo, improves pneumonia symptoms and histopathological changes, and increases the level of FGF2 and protein expression of FGFR1 in the lung." (PMID 33192523, 2020). "PICFLU - The adjusted BS4 module containing EGF, Eotaxin, FGF-2, Fractalkine (FKN), GRO, IFN-α2, IL-12-P70, IL-7, MDC, and sCD40-L was negatively associated with shock, pneumonia-ARDS and ECMO or death (odds ratio 0.463, 0.598, 0.494, FWER-p = 0.0002, 0.0155, 0.0283, respectively)." (PMID 31275311, 2019). "Pneumonia correlates with specific cytokines IFN2, Il-15, IL-7, sCD40L, MCP-1, FGF-2, MIP-1b, MIP-1a, MDC, and GM-CSF." (PMID 37629267, 2023).
rhabdomyosarcoma (4 papers, 1995 to 2025). A rare aggressive malignant mesenchymal neoplasm arising from skeletal muscle. "The rhabdomyosarcoma (hence called CS3) interactions network numbers 46 nodes, where IL-6 and FGF2 are its most connected nodes." (PMID 34359782, 2021).
schizophrenia (4 papers, 2013 to 2024). A major psychotic disorder characterized by abnormalities in the perception or expression of reality. "BDNF, FGF2, and DA are known to be key molecules for the causes and biomarker of schizophrenia." (PMID 23675315, 2013). "Taken together, these results suggest that changes in the quantity and quality, particularly DP, of polySia, which are closely related with the enzymatic activity of ST8SIA2, lead to an altered binding affinities toward BDNF, FGF2, and DA, may be one of the underlying causes of schizophrenia." (PMID 23675315, 2013). "However, studies on other psychiatric disorders reported increased serum levels of FGF-2 in individuals with schizophrenia." (PMID 38414501, 2024). "The duration of schizophrenia was significantly positively correlated with the FGF-2 level." (PMID 37185739, 2023). "The aim of the study was to determine the serum concentration of six growth factors (EGF, VEGF, FGF-2, TGF-α, PDGF-AA, PDGF-AB/BB) in schizophrenia patients and to identify the correlations with clinical characteristics." (PMID 37185739, 2023). "FGF-2 (also known as FGF-beta or bFGF) also enhances the proliferation and differentiation of dopaminergic neurons, which is very important in schizophrenia." (PMID 37185739, 2023). "Thus, our pilot studies, for the first time, showed changes in the TGF-α and PDGF-AA serum levels in schizophrenia patients (especially in female patients) and VEGF in male patients in comparison with healthy persons and an increase in FGF-2 in the long course of the disease." (PMID 37185739, 2023).
scleroderma (4 papers, 2014 to 2025). Scleroderma is a rare autoimmune connective tissue disorder characterized by abnormal hardening of the skin and, sometimes, other organs. "They identified NTN1, VEGFD, MMP2, FGF2, and FNDC5 as potential players in how the ADSCs secretome may disrupt vascular and perivascular inflammation hubs in scleroderma and thereby promote angiogenesis and lymphangiogenesis." (PMID 40584563, 2025). "We found signalling from ADSCs via FGF2 to SDC1 on FB5 in both datasets and FB2 in scleroderma." (PMID 37443817, 2023). "The few effector molecules that were identified, including NTN1, VEGFD, MMP2, FGF2, and FNDC5, provide evidence for the anti-fibrotic and anti-inflammatory effects of the ADSC secretome; however, these few factors cannot explain all observed effects on scleroderma skin after autologous fat grafting." (PMID 37443817, 2023).
synovitis (4 papers, 2005 to 2020). Inflammation of a synovial membrane. "The levels of plasma epidermal growth factor (EGF), colony stimulating factor 2 (CSF2), interleukin 4/13 (IL4/13), fibroblast growth factor 2 (FGF2) and MIP-1 α were significantly lower in patients with a joint bleeding compared to patients without a bleeding or synovitis." (PMID 33023246, 2020).
teratoma (4 papers, 2014 to 2017). A non-seminomatous germ cell tumor characterized by the presence of various tissues which correspond to the different germinal layers (endoderm, mesoderm, and ectoderm). "Additionally, we performed the teratoma formation assay using cells dissociated from the DRG explants cultured for 6 days in the presence of LIF/BMP2/FGF2, and found that teratomas were formed by injecting dissociated DRG cells treated with LIF/BMP2/FGF2." (PMID 28373172, 2017).
uveal melanoma (4 papers, 2012 to 2024). A melanoma derived from melanocytes of the uveal tract. "From the perspective of therapeutic applications, the blocking of endogenous FGF2 with monoclonal antibodies or antisense nucleotide reduced cell proliferation, clonogenic potential, and cell survival in uveal melanoma cell lines." (PMID 35409195, 2022). "Moreover, immunohistochemistry analysis of uveal melanomas showed that, even though FGF2 is mainly located in the cytoplasm of tumor cells, a positive signal is also detectable in the perivascular area." (PMID 35409195, 2022). "Expression analysis in a set of 9 primary uveal melanomas reported that FGF1 and FGF2 were expressed in 77% of samples, with co-expression of FGF1/FGF2 in 55% of cases." (PMID 35409195, 2022). "Indeed, it has been recently reported that FGF2, produced by liver stellate cells, can mediate FGFR activation in metastatic uveal melanoma cells; moreover, it is responsible for the resistance to the bromodomain and histone deacetylase inhibitors." (PMID 35409195, 2022). "In this context, the elevated expression of FGF2 in uveal melanoma metastases further reinforces the hypothesis that FGFs play a non-redundant role in uveal melanoma progression and invasion." (PMID 35409195, 2022).
achondroplasia (3 papers, 2016 to 2021). Achondroplasia is the most common form of chondrodysplasia, characterized by rhizomelia, exaggerated lumbar lordosis, brachydactyly, and macrocephaly with frontal bossing and midface hypoplasia. "For instance, transgenic FGF-2 overexpression results in dwarfism in mice, and activating FGFR3 mutations lead to achondroplasia and shortened long bones with disorganized chondrocyte columns in growth plate." (PMID 31371388, 2019).
alopecia (3 papers, 2015 to 2025). Hair loss usually from the scalp. "In our study, FGF-2 was identified as one of the major target proteins of main medicinal herbs for alopecia treatment." (PMID 35181715, 2022). "Particularly, AChE and fibroblast growth factor receptor 2 (FGF-2) among the findings overlapped with the target protein derived when alopecia was explored as a disease keyword in the GeneCards database." (PMID 35181715, 2022). "Nevertheless, the effect of FGF-1, FGF-2, and FGF-10 in the therapy of hair loss is confirmative and feasible." (PMID 25685806, 2015). "Therefore, the therapeutic effect of the main medicinal herbs on alopecia may involve the modulation of FGF-2 to promote dermal papilla cell proliferation and to prolong the anagen phase by increasing cysteine levels." (PMID 35181715, 2022).